PTK6 (protein tyrosine kinase 6)
Diseases named in the same sentence as PTK6 in open-access papers (continued):
Sharing a sentence is not in itself a finding about the gene and the disease.
tumor (continued). "The effects of PTK6 inhibitors on tumor cell growth were measured in a number of cell lines with various PTK6 expression levels." (PMID 29879184, 2018). "Since these two compounds share similar off-target kinase selectivity, it provides a tool to investigate specifically the role of PTK6 kinase activity in tumor cell growth." (PMID 29879184, 2018). "We also investigated several reported PTK6 substrate candidates that link PTK6 kinase to oncogenic signaling in tumor cells, including Akt, Paxillin, STAT3/5, ERK1/2, p38, FAK and p130CAS." (PMID 29879184, 2018). "Both Type I (and Type II inhibitors as well as PF-6737007 were included in the study to investigate the role of PTK6 kinase activity in tumor cell growth." (PMID 29879184, 2018). "The involvement of PTK6 in tumor growth and invasion through a kinase activity-independent function remains to be further investigated." (PMID 29879184, 2018). "Conversely, downregulating PTK6 levels led to cell death, including in tumor cells that were resistant to tamoxifen and other therapies commonly used to treat estrogen-receptor positive breast cancer." (PMID 29167821, 2017). "Knockdown of PTK6 in PC3 cells inhibited xenograft tumor growth and metastasis, while overexpression of membrane targeted active PTK6 promoted tumorigenesis and the EMT." (PMID 29142193, 2017). "PTK6 downregulation impairs growth of these cells in 3D MatrigelTM cultures, and virtually abrogates primary tumor growth of both tamoxifen-sensitive and resistant MCF-7 xenografts." (PMID 29167821, 2017). "Overexpression of PTK6 in these cells reduced their proliferation in culture and tumor formation in mice." (PMID 27311570, 2016). "92% of B2;Ptk6−/− animals remained tumor free up to 240 days, in contrast to all of the Ptk6-expressing mice that had developed mammary gland tumors." (PMID 26247733, 2015). "B2;Ptk6−/− animals were killed at later time points when tumor burden (mass) was similar to the B2;Ptk6+/+ mice for analyses of tumors and tumor metastasis." (PMID 26247733, 2015). "Recently, the Rab25 and PTK6 genes were identified as tumor suppressors in ESCC, and these two genes were markedly down-regulated in ESCC tumorigenesis both in previous and in this study." (PMID 26158411, 2015). "Recently, a number of protein-coding genes, such as PTK6 and Rab25, have been identified as having tumor suppressor activity through modulating different signaling pathways." (PMID 26158411, 2015). "By 260 days, 58% of the B2;Ptk6−/− animals remained tumor free, whereas all B2;Ptk6+/+ mice had reached humane end points and mice were killed." (PMID 26247733, 2015). "PTK6 associates with ErbB2 and promotes ErbB2-dependent Ras/MAPK signaling, suggesting PTK6 participates in tumour development." (PMID 25748447, 2015). "B2;Ptk6+/− mice developed mammary gland tumors later than B2;Ptk6+/+ animals, and with a lower occurrence and by day 210, ~25% of the B2;Ptk6+/− animals remained tumor free." (PMID 26247733, 2015). "PTK6 is uniformly undetectable in benign lesions or in normal mammary tissues, but it is up-regulated in multiple tumor types, including breast, head and neck, ovarian and lung tumours." (PMID 25748447, 2015). "PTK6 downregulation impairs growth of these cells in in vitro 3-D MatrigelTM cultures, and also inhibits growth of Her2+ primary tumor xenografts." (PMID 26084280, 2015). "PTK6 expression was induced in the mammary glands of ERBB2 transgenic mice before tumor development and correlated with activation of signal transducer and activator of transcription 3 (STAT3) and increased proliferation." (PMID 26247733, 2015). "PTK6 can have an impact on tumor progression and metastasis through its regulation of FAK and BCAR1." (PMID 26247733, 2015). "We have determined that PTK6 promotes tumor initiation and progression and is important for regulation of STAT3, FAK, and BCAR1." (PMID 26247733, 2015).
tumor (continued). "Further studies are required to determine if activation of PTK6 occurs preferentially in specific tumor subtypes and/or high-grade invasive tumors." (PMID 25153721, 2014). "IHC results showed the expression of PTK6 was significantly correlated to tumor size (P<0.001), clinical stage (P<0.001), and metastasis (P=0.016)." (PMID 23758975, 2013). "The localization of PTK6 in normal laryngeal epithelial and tumor tissue cells displayed a primarily cytoplasmic pattern, while a minority of PTK6 was localized in nucleus." (PMID 23497344, 2013). "Multivariate Cox proportional hazards survival analysis indicated that high PTK6 expression in NPC tumor tissues was an independent and unfavorable factor for poor prognosis of NPC patients (P=0.035)." (PMID 23758975, 2013). "This siRNA screen led to the identification of PTK6, a member of the Src family of tyrosine kinases that is frequently overexpressed in a variety of tumor types." (PMID 20668531, 2010). "Most PTK6 copy number gains are modest and with the exception of one tumor, are broad (∼2.8Mbp) gains." (PMID 20668531, 2010). "PTK6 expression in tumour tissue significantly correlated (P⩽0.05) with the expression of PTEN, MAPK, P-MAPK, and Sam68." (PMID 18781181, 2008). "The histological grade of tumours was significantly associated with HER1, HER4, and with PTK6, and an inverse correlation was identified between the oestrogen receptor (ER) and HER 1 (⩽0.04)." (PMID 17299391, 2007). "Here, the stepwise selected parameters were tumour size (relative risk 3.4), HER2 (1.5), and PTK6 (0.4)." (PMID 17299391, 2007). "PTK6 is a critical regulator of key cellular processes, including proliferation, invasion, migration, and epithelial-mesenchymal transition, which collectively contribute to tumor development." (PMID 40809015, 2025). "This inverse relationship suggests that tumors with high PTK6 expression may have low expression of key immune checkpoints, thereby affecting the tumor immune microenvironment and modulating the response to immune checkpoint inhibitor therapy." (PMID 40809015, 2025). "Interestingly, in PDAC, elevated PTK6 levels are shown to attenuate tumor growth in vivo after gemcitabine treatment in vivo." (PMID 38650175, 2024). "Then, PTK6 expression has been examined at different stages of tumor." (PMID 38573548, 2024). "In addition, MARCH2 overexpression suppresses growth, invasion, and metastasis of TNBC, exhibiting tumor suppressive properties, and phenocopying effects of PTK6 or SNAIL inhibition." (PMID 38457262, 2024). "In addition, the level of PTK6 mRNA was also significantly increased in tumor compared to their adjacent normal tissues." (PMID 38573548, 2024). "To investigate whether inhibition of PTK6 can prevent tumor cell invasion, we conducted wound healing and invasion experiments." (PMID 38573548, 2024). "This suggests that PTK6 not only plays a tumor-promoting role by inhibiting autophagy in UM but might also play a role by suppressing the autophagy pathway in other disease models." (PMID 36690663, 2023). "Besides the lipid phosphatase activity against PI3K/Akt signaling pathway, the protein phosphatase activity of PTEN against oncogenic factors such as the phosphoglycerate kinase 1 and the tyrosine kinase PTK6 also is essential in tumor suppression." (PMID 36774408, 2023). "While it is clear that PTK6 can promote the proliferation and migration of tumor cells, the specific mechanism and signaling pathway is still unknown." (PMID 37932734, 2023). "The overexpression of PTK6 significantly increased tumor volume and weight." (PMID 35562900, 2022). "Ptk6 (Brk) expression was shown to enhance the formation of murine ErbB2-induced tumours in cleared fat pads with a shorter latency period than ErbB2-only tumours, and both constitutively active and wild-type Brk promoted xenograft growth of MDA-MB-231 basal breast carcinoma cells." (PMID 35327957, 2022).
tumor (continued). "PTEN, a tumor suppressor, negatively regulates PTK6 activity by dephosphorylating PTK6 on Tyr342." (PMID 36228719, 2022). "Moreover, IHC results of clinical CRC samples collected from Nanfang hospital further demonstrated that high PTK6 expression was detected in 55.6 % (90/162) of the tumor tissues compared with that in 34.5 % (20/58) of the adjacent normal tissues." (PMID 34551797, 2021). "Therefore, PSPC1 is the contextual determinant for the reciprocal oncogenic subcellular translocation of cytoplasmic PTK6 and nuclear β-catenin to exert synergistic effects on oncogenic tumor progression." (PMID 34340703, 2021). "An innovative dual inhibitor derived from a unique C-terminal polypeptide composed of 131 amino acids of PSPC1 targeting both oncogenic PSPC1 and PTK6 nucleocytoplasmic shuttling was shown to exhibit synergistic tumor-suppressive effects in HCC cell lines and mouse models." (PMID 34340703, 2021). "In this study, we demonstrate that PTK6 is targeted by miR-214, a tumor suppressor microRNA." (PMID 31278310, 2019). "Collectively, these results demonstrated that PSPC1-CT131 could interact with PSPC1, PSPC1-Y523F, and p-PTK6 in the nucleus to abrogate their synergized functions in tumor progression." (PMID 31844057, 2019). "The ability of PSPC1-Y523F to revert the tumor suppressive function of the PTK6/PSPC1 axis raised a hypothesis that this mutant might promote the shuttling of PTK6 from nucleus to cytoplasm." (PMID 31844057, 2019). "Ectopic expression of PTK6 in engineered cells may have a different intracellular location from the endogenous PTK6 in tumor cells given the known flexibility of the intracellular location of PTK6 in different cell types." (PMID 29879184, 2018). "This cell type-dependent spatial distribution of PTK6 in engineered cell lines may account for the poor translation of PTK6 substrate candidates identified from engineered cell lines to tumor cells." (PMID 29879184, 2018). "From this study, a moderate tumor cell growth inhibition by PTK6 inhibitors was observed." (PMID 29879184, 2018). "Drugs that target a tumor-promoting enzyme called protein tyrosine kinase 6 (PTK6) could help treat hormone-receptor positive breast cancer." (PMID 29167821, 2017). "However, most studies showed that PTK6 was a potential oncogene and played a role in tumorigenesis and tumor development." (PMID 27311570, 2016). "In vitro studies showed that PTK6 promoted tumor cell migration, invasion, and proliferation." (PMID 27311570, 2016). "PTK6 downregulation also suppressed growth of UACC893R1 primary tumor xenografts." (PMID 26084280, 2015). "B2;Ptk6+/+ animals were maintained until they reached the humane end point (tumor >2 cm)." (PMID 26247733, 2015). "In contrast, in many tumor model systems PTK6 promotes survival." (PMID 26084280, 2015). "Complete disruption of Ptk6 markedly delayed tumor initiation." (PMID 26247733, 2015). "Taken together, these findings indicated that PTK6 might play an important role in the tumor differentiation and progression of LSCC." (PMID 23497344, 2013). "Furthermore, the high expression of PTK6 was significantly correlated to tumor size (T classification), clinical stage, and metastasis, respectively (P<0.05)." (PMID 23758975, 2013). "Therefore, elevated PTK6 expression in tumour tissue is presumably accompanied by alterations to the expression levels of multiple other molecules." (PMID 18781181, 2008). "Most of these overexpressing tumours show co-overexpression with PTK6, as shown in." (PMID 18781181, 2008). "The data concerning PTK6 expression in tumour tissues are, so far, very limited." (PMID 18781181, 2008). "To get an indication whether these statistical correlations of markers in tumour tissue may be caused by molecular associations with PTK6, we used IP and found that Sam68, PTEN, MAPK, and P-MAPK all coprecipitate with PTK6." (PMID 18781181, 2008).
tumor (continued). "Metastases-free survival of patients for longer than 240 months was inversely associated (P⩽0.05) with nodal status, tumour size, and oestrogen receptor status, but was also directly associated with high protein expression levels of HER4 and PTK6 in Kaplan–Meier analysis." (PMID 17299391, 2007). "Thus, targeting PTK6 could disrupt tumor progression and metastasis, suggesting that developing selective small molecule inhibitors or monoclonal antibodies against PTK6 may provide a novel therapeutic approach." (PMID 40510341, 2025). "Furthermore, PTK6 plays a role in regulating tumor angiogenesis and apoptosis." (PMID 40809015, 2025). "This implies that tumor aggressiveness and size may be related with PTK6 in LUAD." (PMID 38573548, 2024). "Finally, Annexin V/PI staining experiments were performed to examine whether suppressing PTK6 could diminish tumor cell apoptosis." (PMID 38573548, 2024). "PTK6 was shown to phosphorylate and yield a cytoplasmic re-localization of the PTB-associated splicing factor (PSF) from the nucleus, resulting in cell cycle arrest, a function consistent with reports of the pro-tumor suppressive role of PTK6 within the nucleus." (PMID 37509364, 2023). "Therefore, it is likely that kinase inhibition of PTK6, in combination with chemotherapies, would still be effective therapeutically but may depend on tumor context." (PMID 37509364, 2023). "We found that the tumor progression gene signatures associated with metastasis, stemness, and the C-Myc, TGF-β1, Wnt/β-catenin, and PTK6 oncogenic pathways were significantly upregulated in cells expressing the PSPC1, PSPC1-Y523F, and PSPC1-Y523F/PTK6 constructs." (PMID 31844057, 2019). "Despite the intensive studies of PTK6 function in normal cells and tumor cells, the PTK6-dependent signaling pathways that regulate various cellular processes is poorly understood, and the specific role of PTK6 kinase activity in tumor formation and growth remains unclear." (PMID 29879184, 2018). "Thus, data from the literature and our study suggest that PTK6 may act as an oncogene in tumor initiation and progression." (PMID 27311570, 2016). "Some studies indicated that PTK6 may act as a tumor suppressor gene." (PMID 27311570, 2016). "In normal epithelial cells, nuclear PTK6 expression is related to the regulation of cell growth, whereas cytoplasmic PTK6 expression may promote tumorigenesis by activating oncogenic signaling pathways in tumor cells." (PMID 27311570, 2016). "This ceRNA network suggests that PTK6 is not only directly regulated as a downstream effector molecule of mRNA but may also participate in regulating the proliferation, invasion, and immune environment remodeling of tumor cells through the non-coding RNA network." (PMID 40809015, 2025). "Overexpression of MARCH2 exhibits tumor suppressive properties and phenocopies the effects of SNAIL downregulation and PTK6 inhibition in TNBC cells, such as inhibition of migration, anoikis resistance, and metastasis." (PMID 38457262, 2024). "Hub genes with high centrality, including PTK6, FGFR3, and FGFR4, which have been recognized as therapeutic targets in tumor treatment." (PMID 38347596, 2024). "According to this study, PTK6 expression was positively correlated with CD160, IL10RB, and PVRL2 while being negatively correlated with ADORA2A, BTLA, CSF1R, and KDR in the other tumor types." (PMID 38573548, 2024). "The identified epigenetic PARPi hallmarks contained hundreds of DMRs; however, only a few DMRs were reported as tumor driver genes (SOX2, POU2AF1, PTK6, VHL, JAK3, and EZH2) or as HRD genes (RAD51C)." (PMID 38927686, 2024). "In vitro experiments with ECA-109 and KYSE-150 and ex vivo experiments in tumor-bearing mice were performed to investigate the effects of FSCN1 and Protein Tyrosine Kinase 6 (PTK6) on ESCC progression." (PMID 35401239, 2022).
tumor (continued). "PTK6-T2 blocked the binding between FSCN1 and the pre-mRNA of PTK6, and thus reversed the promotion effect of FSCN1 on ESCC tumor progression via the AKT/GSK3β signaling pathway." (PMID 35401239, 2022). "PTK6 was identified via its interaction with PSPC1 in the nucleus by proteomic analysis and acts as a tumor suppressor to abrogate the oncogenic effects of PSPC1." (PMID 34340703, 2021). "PSPC1 also facilitates the cytoplasmic translocation of protein tyrosine kinase 6 (PTK6) to become an oncogene, and β-catenin nuclear translocation to interact with PSPC1 for augmenting Wnt3a autocrine signaling and tumor progression." (PMID 34359789, 2021). "Respectively, the expression of CDO1, CELF2, ITPRIPL1, KCNH8, RIC3, USP44 and ZSCAN23 was significantly lower in tumor tissues, whereas the expression of PTK6 and RAB25 was significantly higher in tumor tissues." (PMID 34056873, 2021). "We thus tested this synergism in tumor promotion by coexpression of PTK6 and PSPC1-Y523F in SK-hep1 cells or by expressing PSPC1 or PSPC-1-Y523F in PTK6 highly expressed SNU-387 cells." (PMID 31844057, 2019). "Our results indicated that PSPC1-Y523F expression shifts the preference of its nuclear partner from PTK6 to β-catenin, which likely contributes to the functional synergism between PSPC1 and cytoplasmic PTK6 in tumor promotion." (PMID 31844057, 2019). "To dissect the functional consequences of PSPC1 phosphorylation by PTK6, we expressed the phosphorylation-defective mutant PSPC1-Y523F to test its effect on the tumor suppressive functions of the PTK6/PSPC1 axis, and PSPC1-Y383F was included as a control." (PMID 31844057, 2019). "Together, our data suggest that nuclear PTK6 forms a complex with tyrosine-phosphorylated PSPC1, which suppresses the tumor progression effects of PSPC1." (PMID 31844057, 2019). "To further confirm the disconnect between PTK6 kinase activity and tumor growth, we overexpressed PTK6 WT in MDA-MB-231 cells, and compared the compound potency of PTK6 kinase inhibition vs. tumor growth inhibition in the engineered MDA-MB-231 cells." (PMID 29879184, 2018). "To examine tumor metastasis, we collected lung tissues from Ptk6+/+ and Ptk6−/− MMTV-ERBB2 transgenic mice with similar total tumor burden, which included mice aged 243±15 days (Ptk6+/+) and 364±33 days (Ptk6−/−)." (PMID 26247733, 2015). "To explore contributions of PTK6 to mammary gland tumorigenesis promoted by activated ERBB2, we crossed Ptk6−/− mice with the mouse mammary tumor virus-ERBB2 transgenic mouse line expressing activated ERBB2 and characterized tumor development and progression." (PMID 26247733, 2015). "The reduced PTK6 mRNA expression in LSCC was observed in 11 of the 13 cases, suggesting that the mRNA level of PTK6 was significantly lower in tumor tissues than in paracancerous epithelium tissues." (PMID 23497344, 2013). "Brk/PTK6 and HIF 1-α were also down-regulated by MSM, showing the multiple target action of this compound for tumor suppression." (PMID 22485142, 2012). "For some tumor cells within a sample, there was also an observed increase in the number of hybridized signals with the Chromosome 20 centromere-specific probe, suggesting that in some cases apparent PTK6 copy number gains may be due to increased numbers of chromosome 20." (PMID 20668531, 2010). "The comparison of protein expression between the markers in tumour tissue showed that Sam68, PTEN, MAPK, and P-MAPK are all significantly correlated with PTK6 expression." (PMID 18781181, 2008). "We further found a correlation between PTK6 expression and the levels of MAPK and P-MAPK in tumour tissues." (PMID 18781181, 2008). "We identified a high co-overexpression of PTK6 less frequently with HER1 or HER2 (less than 18%), and more frequent with HER4 (34%) and with HER3 (40% of the tumours)." (PMID 17299391, 2007).